CD69 (CD69 molecule)
Diseases named in the same sentence as CD69 in open-access papers (continued):
Sharing a sentence is not in itself a finding about the gene and the disease.
tumor (continued). "The expression levels of IL7R, CD69, and PTPRC and the TNM stages of the tumor were significantly related to the OS rate of SKCM patients." (PMID 36032150, 2022). "The CD69− TTE cells showed oligoclonal expansion and the ability to lyse autologous tumor cells, while CD69+ TTE cells exhibited low perforin and granzyme expression and increased immune checkpoint expression." (PMID 35563634, 2022). "We demonstrate that Vγ9Vδ2 T-cells are selectively reduced in frequency in the blood, livers, and tumours of patients with HCC, but display the capacity to acquire an intratumoural γδ TRM (CD69+CD49a+ or CD69+CD103+) phenotype." (PMID 35296658, 2022). "We then compared the mRNA levels of CD69 and SBK1 in tumor versus normal tissues using TCGA and GTEx datasets." (PMID 36045683, 2022). "To better understand the functions of CD69 and SBK1 in the tumor immune microenvironment, we carried out a comprehensive pan-cancer analysis using TCGA data." (PMID 36045683, 2022). "In lung cancer patients, high densities of mature dendritic cells (Lamp+) positively correlated with infiltration of activated CD8+ T cells (CD69+ CD38+) and with an effector memory phenotype that localized in the tumor nest, close to target tumor cells." (PMID 35874810, 2022). "Results showed that a combination of anti-PD-1 plus anti-TGF-β had only a marginal effect on tumour growth and infiltration by TIL and CD8+ T cells, even though a decrease in the percentages of CD103+CD69+CD8+ T cells was observed." (PMID 34471106, 2021). "Infiltration of both activated CD4+CD69+ T cells and regulatory Foxp3+CD4+ T cells into HNSCC tumor tissue contribute to prognosis." (PMID 33732250, 2021). "CD69, CD103, CD39, and CD49a are the key biomarkers of tumor-reactive CD8+ Trm cells and can be used as prognostic molecules for different digestive tract tumors." (PMID 35096624, 2021). "In fact, the pattern of elevated PD-1 and decreased CD69 was observed on CD103+ CD4 or CD8 TILs, linking tumor residency to specific degree of TIL activation status." (PMID 34680397, 2021). "Decreased the functional activity of spleen-derived NK cells and downregulated the expression of the activating receptors CD69 and NKG2D; reduced NK cells’ ability to kill tumor cells." (PMID 33530529, 2021). "Remarkably, CD8+ T cells from B16F10E-KO were more enriched with KLRG1+ effectors and activated CD69+ cells, and less enriched with CD103+ cells than B16F10E, which correlated with a decreased production of active TGF-β by the former tumours." (PMID 34471106, 2021). "We sorted tumor CD44hiCD103−CXCR6+PD-1+ TEff/EM cells and CD103−IL7R+IL18R1+ TEff/EM cells, as well as tumor and distant TRMs (CD103+CD69+) for repertoire analysis and clonotype lineage tracing." (PMID 33979626, 2021). "Consistent with the observations of tumor-infiltrating NK cells, downregulation of METTL3 protein level in NK92 cells induced decreased expression of activation receptors, such as CD69, NKp30, and NKG2D, the transcription factor T-bet, and IFN-γ." (PMID 34535671, 2021). "It is possible that BM-resident CD69+ TTE and circulating CD69- TTE cooperate in anti-tumor immunity based on the inverse relationship between CD69+ TTE and CD69- TTE observed within the BM-resident T cell compartment in NDMM patients." (PMID 33708212, 2021). "Tumor-infiltrating CD8+ T cells, CD69+ T cells, and perforin were also increased after ES-DSM + MW treatment." (PMID 34362890, 2021). "CD25 and CD69 staining revealed a higher expression in CD4+ and CD8+ subsets in the BM compared to the spleen, which correlated with observed tumor burden." (PMID 33414484, 2021). "In contrast, CD69+CD103+ T cells from untreated and anti-PD-1-treated B16F10E and B16F10E-KO tumours displayed similar percentages of Ki-67+ lymphocytes." (PMID 34471106, 2021). "These cSCC CD69+/CD103+ TRMs exhibited increased IL-10 production, and higher CD39, CTLA-4 and PD-1 expression compared with CD103− TRMs in the tumor." (PMID 33479027, 2021).
tumor (continued). "After stimulation, the percentage of C02-Activated-IFNG and C06-Activated-IL2RA of TCR-TMART-1 was downregulated, while the fragment of C01-Activated-CD69, C11-Activated-IL15, and C12-Cytotoxic-GNLY was upregulated with increased tumor PD-L1 levels." (PMID 33754038, 2021). "In this regard, the opposed expression of PD-1 and CD69 on specific T cells, as well as CD80 and PD-L1 on APCs in tumor vs. colon tissue, suggest discrete activation patterns in these tissues." (PMID 34680397, 2021). "E0771 tumor-bearing fat pad-infiltrating CD4 and CD8 T cells expressed elevated CD69, PD1, CTLA4, and CD25; with increased Tregs expressing inhibitory receptors PD1 and CTLA4." (PMID 33767151, 2021). "The distinct milieus of tumor and colon are likely reflected on the opposed expression of CD80 and PD-L1 on MPs, as well as PD-1 and CD69 on CD8+CD103+CD39+ T cells." (PMID 34680397, 2021). "In the meantime, the increases in the percentages of CD4+ and CD8+ T cell, CD4+CD69+ and CD8+CD69+ T cell were found in tumor tissue and in lymph node near the tumor." (PMID 33816301, 2021). "Immunofluorescence staining of tumour tissue confirmed that CD69+CD8+ T cells were increased in abundance in situ and localised to the primary tumour at this early stage." (PMID 33513866, 2021). "Significant increases of CD69, IFNɣ, CD107a, CD314, and NKp46 in tumor infiltrated NK cells in LDHA knockout xenograft tumor." (PMID 34482375, 2021). "These cells express the integrins CD103 and CD49a and the C-type lectin CD69, and are characterized by in situ proliferation, location and persistence in close contact with malignant cells, via binding of CD103 to tumor E-cadherin." (PMID 33329534, 2020). "Surprisingly, we didn’t observe any PD-L1 up-regulation of CARPD-L1z T cells either activated by CD3/CD28 antibodies or co-cultured with PD-L1+ tumor cells, even the percentage of CD25 and CD69 double-positive T cells confirmed they fully activated." (PMID 32514352, 2020). "Previous studies have demonstrated that CD69-deficient mice or those treated with anti-CD69 antibody therapy have reduced tumor growth rate and metastatic burden, however, our study clearly demonstrates that anti-CD69 treatment alone or in combination with PI-3065 did not result in tumor control." (PMID 33093155, 2020). "It was demonstrated that anti-PSCA CAR-T cells were fully activated after coculture with target tumor cells, as indicated by their upregulation of CD25 and CD69." (PMID 32010446, 2020). "We also examined expression of the activation markers CD69, 41BB, and CD25 at 24 and 72 hours after stimulation with LM7 tumor cells." (PMID 33148882, 2020). "The expression of the activation markers CD69 and CD44 was substantially upregulated on CD4+ and CD8+ tumor-infiltrating T cells in M1-treated mice, indicating the reinvigoration of T-cell populations." (PMID 33311488, 2020). "Thus, it remains unclear whether CD69+CD103+T cells are true TRM cells or alternately the expression of these molecules identifies effector T-cell subsets that have infiltrated the tumor bed where abundant TGF-β found in a large quantity in many tumors drives CD103 expression." (PMID 32695313, 2020). "Tumor infiltrating innate lymphoid cells (ILCs) can show an activated phenotype (expression of CD69, CD44, MHCII, and KLRG1) and provide tumor immunosurveillance." (PMID 33266109, 2020). "Vitiligo‐affected skin was shown to have CD8+ T cells recognizing tumor/self‐antigens and to exhibit a TRM cell phenotype (CD44hi CD62Llo CD69+ CD103+)." (PMID 31230406, 2019). "In comparison, tumor-specific CD8+ T cells in spleens, DLN and NDLN largely maintained IL-7R expression despite CD44 upregulation, and upregulation of CD69 was observed predominantly within the DLN." (PMID 31998326, 2019).
tumor (continued). "In the mouse tumor model, F5 T cells are exposed to NP68 cognate peptide expressed on tumor cells and to exogenously injected or tumor derived peptide on APC in spleen and LN, as evidenced by CD69 upregulation at these sites." (PMID 31249570, 2019). "Following TfR-BiTE-mediated tumor lysis, both CD8 and CD4 T-cell subsets maintained an activated phenotype as shown by expression of the early activation marker CD69 and cytotoxic granule granzyme B (GrB)." (PMID 31293575, 2019). "As such, lung and tumor derived CD4+ and CD8+ T cells can be divided into three populations based on the expression of CD69 and CD103 (CD103+CD69+, CD103−CD69+, and CD103−CD69−)." (PMID 30505306, 2018). "Results showed that the peptide-sensitized CTLs had a higher CD69+ T-cell subset and produced IFN-γ in response to tumor cell recognition." (PMID 29515106, 2018). "Characterized by cell-surface molecules including CD103, CD69, and CD49a, TRM-like tumor-infiltrating lymphocytes (TILs) can be found in a wide range of human cancers, where they portend improved prognosis." (PMID 30555481, 2018). "Tumour infiltrating ILC were found to show an activated phenotype with higher expression of MHC-II, KLRG1, early activation marker CD69 and CD44." (PMID 29587679, 2018). "As with tumor cell killing, all three anti-CD3 reagents enhanced CD25 or CD69 up-regulation by the γδ T cells." (PMID 30038626, 2018). "Both ascites and control NK cells showed high CD69 expression, while TRAIL levels decreased upon tumor challenge." (PMID 30410679, 2018). "CD69 is also expressed on recently activated T cells and there was a trend that the CD39+ Treg in the tumor had higher expression of CD69." (PMID 30651930, 2018). "Evaluating the phenotype of tumour infiltrating ILC in breast and malignant GI carcinomas showed a significantly higher frequency of ILC expressing the early activation marker CD69 compared with circulating innate lymphocytes." (PMID 29587679, 2018). "For the rest of paper we refer to the CD103+CD69+ and CD103−CD69+ tumor and lung populations as CD103+ and CD69+ TILs and TRM, respectively, and tumor and lung CD103−CD69− as CD69− TILs and CD69− T cells, respectively." (PMID 30505306, 2018). "Skin OT-I Trm cells expressing CD69 and CD103 were found 20 days and 45 days after tumour inoculation." (PMID 28714465, 2017). "After pneumonectomy for isolated tumours, histologically normal human lung tissue far from the tumours contains both CD4 and CD8 cells with diverse T cell receptors (TCR) that express CD69, produce TNFα and IFNγ and proliferate in response to influenza virus." (PMID 28475122, 2017). "There was a significant increase of CD69 expression on NKT cells in the inflammation group and tumor group compared to that of the healthy group." (PMID 28977824, 2017). "These T cells in operated animals are active (CD8+CD69+) and cytotoxic (CD8+GrB+), similar to our observation in NLGP-treated tumor hosts." (PMID 28414726, 2017). "Early activation markers, CD69 and CD25 were both upregulated upon T cell stimulation in co-culture with tumor cell/fibroblasts." (PMID 28750018, 2017). "Most CD3+CD56+NKT-like cells in GC tumors were CD45RA−CD27+/− central/effector-memory cells with decreased activity and lower expression levels of CD69, NKG2D and DNAM-1 than those in non-tumor tissues." (PMID 27409423, 2016). "CD69+CD8+ cells are present in the tumor cell area, whereas outside the tumor area CD8+ cells expressed the late activation marker CD25+." (PMID 27999289, 2016). "Anti-Nrp-1 not only allowed the increased expansion of tumor-derived CD4+CD8a− T cells, but it also activated tumor-derived CD4+ T cells (CD4+CD69+) in IL-10−/− and WT B16/F10 mice." (PMID 27075020, 2016). "PD-1+CD4+ and CD69+ T-cells were located inside, and Tregs and CD25+CD8+ cells outside the tumor cell area." (PMID 27999289, 2016).
tumor (continued). "Furthermore, they found a positive correlation between serum levels of Hsp70 with gross tumor volume and an inverse correlation with CD69+/CD94+ NK cells in squamous NSCLC, suggesting that activated NK cells somehow may be involved in the control of tumor growth." (PMID 27446079, 2016). "LP cells in NLPHL are surrounded by PD-1+CD4+ and CD69+CD4+ cells with a TEM phenotype, while levels of Tregs and CD25+CD8+ cells are increased outside the tumor cell area." (PMID 27999289, 2016). "Cx mice also exhibited an increase in activated (CD25+CD69+) CD4+ and CD8+ T cells in the inguinal lymph node draining the tumour site." (PMID 22880080, 2012). "Pomalidomide induced expression of CD69 accompanied by a more than twofold increase of IFN-γ production and enhanced killing of K562 tumor cells." (PMID 23316191, 2012). "A population of spleenic CD4+CD69+, but CD25− and FoxP3−, T cells with regulatory activity has been described in tumor-bearing mice." (PMID 22319577, 2012). "Tumor-bearing ST2−/− mice had significantly higher percentages of activated CD27highCD11bhigh NK cells, CD69+ and KLRG− NK cells and higher cytotoxic activity of splenocytes, NK cells, and CD8+ T cells in vitro." (PMID 21484786, 2011). "Both MTB and CW induced the expression of the CD69 activation marker on human CD3- CD56+ NK cells, and enhanced the expression of CD107a when exposed to K562 tumor cells in vitro." (PMID 20331905, 2010). "CFSE-stained cells found in the tumor draining lymph nodes on day 3 were 30% CD8+, 72% CD4+, 95% CD44+, and 39% CD69+." (PMID 21050466, 2010). "Mixed Jurkat T cells were recovered from the tumor cell monolayer by EDTA treatment, ficoll purified, washed twice with medium and incubated with anti-CD69 PE mAb." (PMID 19777065, 2009). "Tumour-infiltrating lymphocytes were both of the CD4 and CD8 subsets and the majority presented an activated CD69+ phenotype." (PMID 16641897, 2006). "Furthermore, in tumor tissues, naïve T-cells exhibited higher expression levels of CCR7, whereas, in normal tissues, naïve T-cells displayed increased CD69 expression." (PMID 41186645, 2026). "Accordingly, the frequencies of CD69 and CD103 expressing cells were dramatically higher in both CD4+ and CD8+ T cells’ population from tumor samples than from PB, both in the case of W‐L GBM and in the case of all the three layers of 5‐ALA resected GBM, compared with PB." (PMID 40498413, 2025). "The majority of these tumor-infiltrating CD4+ T cells were activated (CD69+); however, the activation was not influenced by 2015." (PMID 39820127, 2025). "Upon exposure to tumor cells, T cells from PWH showed significantly increased expression of exhaustion markers (LAG3, PD-1, TIM3, and CD39) but decreased expression of activation markers (CD25 and CD69) compared with T cells from PWOH." (PMID 40459946, 2025). "The addition of NY_1xCD3_v3 induced a dose-dependent increase in the activation markers CD25 and CD69 on CD8+ T cells in the presence of all HLA-A∗0201/NY-ESO1157-165 (9C)-positive tumor cell lines, but not in antigen-negative cells." (PMID 41321628, 2025). "Additionally, leptin exposure in human NK cells also upregulated CD69, boosted IFN-γ secretion, and strengthened tumor cell conjugate formation, partly through increased expression of tumor necrosis factor-related apoptosis-inducing ligand (TRAIL)." (PMID 41516046, 2025). "In contrast, the tumor-specific cluster C3 appears less differentiated with features typical of CD56brightCD16neg NK cells (NCAM1, CD2, CD27, SELL, CD69) as well as a signature of tissue residency (CD69 and ITGA1) and of TGF-β-induced genes (SMAD7, TGFB1, PMEP1, SKIL)." (PMID 41145419, 2025). "Compared to the vehicle and Y332D monotherapy, the RT plus Y332D therapy significantly increased the tumor‐infiltrating abundance of lymphocytes, CD3+ T, CD8+ T, activated CD8+ T (CD25+/CD69+ CD8+), cytotoxic CD8+ T (Gzmb+ CD8+ T and IFN‐γ+ CD8+ T), and proliferating CD8+ T (Ki67+ CD8+ T) cells." (PMID 40470716, 2025).
tumor (continued). "While the proportion of CD4+CD25highCD127low regulatory T cells (Treg) was numerically highest in MPE (6.9% in MPE vs. 3.8% in tumor vs. 4.2% in blood), MPE Tregs possessed lower levels of activation markers (CD69, HLA-DR) and co-inhibitory receptor (PD-1, LAG-3, TIM-3) expression." (PMID 41415427, 2025). "Flow cytometry analysis revealed an increase in the proliferative (Ki67+), activated (CD69+), and cytotoxic (TNFα+, IFNγ+, GzmB+) CD8+ and CD4+ T cells in tumor tissues and spleens of GL261 tumor-bearing mice treated with cinobufagin, compared to the vehicle-treated group." (PMID 39901195, 2025). "However, CD69+CD4+ T cells barely expressed CD103 compared with CD69+CD8+ T cells, and slightly lower frequencies of CD69+CD8+ T cells were observed in the tumor tissues than in liver tissues." (PMID 40361474, 2025). "The CTLs expressing activation markers CD69 and CD62L was also increased by greater than 4-fold in the mIL12 mRNA treated tumors compared to control tumors indicating an active CTL mediated anti-tumor response environment." (PMID 40321762, 2025). "In contrast, CD8 effector cells exhibited downregulation of multiple key genes involved in tumor-suppressive transcriptional regulation (HIST1H1C, ZNF331, KLF6, and BTG1) and immune activation and trafficking (CXCR4, CD69, and TNFAIP3) in LS carriers, which was more severe in LS-CRC." (PMID 40909768, 2025). "The CTLs expressing activation markers CD69 and CD62L were also increased by greater than fourfold in the mIL12 mRNA-treated tumors compared to control tumors indicating an active CTL-mediated anti-tumor response environment." (PMID 40560386, 2025). "Similarly, the expression levels of CD25, CD69, and effector molecules IFNγ and GZMB were significantly increased in T cells co‐cultured with I3A‐treated B16‐OVA tumor cells." (PMID 40583248, 2025). "Tumor-infiltrating T cells with upregulated expression of activation markers, such as CD44, CD69, and CD25, and downregulated expression of exhaustion markers like PD-1 and CTLA-4 indicate a higher T-cell functional status that mediates a stronger and more enduring anti-tumor response." (PMID 40867322, 2025). "Considering that CD69+CD103+CD8+ T cells in the liver and tumor tissues influence RFS differently, their contributions to tumor immune surveillance and tumor progression may depend on their specific location." (PMID 40361474, 2025). "To explore the importance of metabolism on the features of iNKT cells, we simultaneously investigated the metabolic profiles of iNKT cells and the expression of an activation marker (CD69) and ICPs (PD1 and LAG3), whose expression was highly modulated in tumor-infiltrating iNKT cells." (PMID 41562072, 2025). "Interestingly, these CD103+CD69+CD8+ TRM cells can be suppressed by the gastric microbiome, particularly Methylobacterium, leading to tumor immune escape and a poor prognosis for patients with GC." (PMID 39802636, 2025). "Furthermore, the percentage of Ly108− and CD69+ T cells, which are characteristic of exhausted CD8+ T cells that still retain significant cytotoxic potential, was also high in the tumor." (PMID 40343532, 2025). "A greater proportion of tumor-infiltrating CD8+ T cells expressed the activation marker CD69 after OSU13 treatment compared with no-drug control." (PMID 38900577, 2024). "Notably, hYP218 CAR T cells were maintained in an activated state in the tumour microenvironment, indicated by the expression of CD39 and CD69 markers along with increased IFNγ, and TNFα secretion." (PMID 39548594, 2024). "In addition, surface expression of T cell activation markers CD69 and CD25 elevated in both CD8+ and CD4+ T cells in the presence of CFPAC-1 tumor cells and HLA-G12V/CD3 BiTE." (PMID 38752985, 2024). "Therefore, we measured the distribution of CD4+ T, CD8+ T, and activated CD8+ T cells (CD69+CD8+) in peripheral blood, sentinel lymph nodes, and tumor-bedding sites." (PMID 38279092, 2024).